FGFR3 (fibroblast growth factor receptor 3)
Diseases named in the same sentence as FGFR3 in open-access papers (continued):
Sharing a sentence is not in itself a finding about the gene and the disease.
skeletal dysplasia (89 papers, 2008 to 2026). Any Mendelian diseases that affects growth and development of the skeleton. "Four pathogenic missense variants in FGFR3 were found in 9 cases (case 3084, 2079, 6411, 5588, 3078, 3031, 2919, 4714, 4743) with skeletal dysplasia." (PMID 37880672, 2023). "Gain-of-function FGFR3 mutations have been shown to prolong FGFR3 signaling and disrupt proper chondrocyte proliferation and differentiation, leading to a group of skeletal dysplasias of varying severity." (PMID 37824212, 2023). "It is the most common lethal skeletal dysplasia, caused by different FGFR3 mutations that give rise to more severe biological consequences than seen in achondroplasia." (PMID 34693503, 2022). "This well-known skeletal dysplasia is caused by gain-of-function mutations in the FGFR3 gene, which cause generalized impairment of endochondral bone formation but not intramembranous bone formation." (PMID 34693503, 2022). "Genetic disorders associated with skeletal dysplasia include many genes involved in growth plate development, such as FGFR3, ACAN, NPR2, FBN1, and IHH, which can cause varying degrees of short stature with or without other minor abnormalities." (PMID 35250876, 2022). "Mutations in fibroblast growth factor receptor 3 (FGFR3) are known to cause several kinds of skeletal dysplasia accompanying AN." (PMID 30635042, 2019). "This mouse model offers a tool for assessing potential therapeutic approaches for skeletal dysplasias related to over-activation of human FGFR3, and for further studies of the underlying molecular mechanisms." (PMID 28230213, 2017). "Gain-of-function point mutations in fibroblast growth factor receptor 3 (FGFR3) cause a variety of congenital skeletal dysplasias inherited as an autosomal dominant trait." (PMID 28230213, 2017). "TD is the most frequent lethal skeletal dysplasia caused by mutation of the fibroblast growth factor 3 (FGFR3) gene." (PMID 27006844, 2016). "For the purpose of this study, we highlight the fact that unambiguous functional mutations in FGFR3 are involved in several diseases, including skeletal dysplasia and osteoarthritis." (PMID 26445212, 2015). "This mutation is present in most cases of skeletal dysplasia and is responsible for the overexpression of FGFR3 that, in the presence of its ligand, FGF9, results in toxic effects leading to altered cellular growth." (PMID 26445212, 2015). "Based on a large number of cases, we report the mutation frequency in FGFR3 for four major skeletal dysplasias." (PMID 25614871, 2014). "FGFR3 is a negative regulator of bone growth, missense mutations in which cause a wide range of skeletal dysplasias." (PMID 24476948, 2014). "Hypochondroplasia (HCH; MIM# 146000) is a mild form of skeletal dysplasia caused by heterozygous activating germline mutations in FGFR3." (PMID 25505998, 2014). "Activating FGFR3 mutations will exacerbate the growth-inhibitory action on chondrocytes, resulting in varying degrees of severity of skeletal dysplasia as per mutation type." (PMID 25505998, 2014). "This study provides valuable information on FGFR3 mutation frequency of four skeletal dysplasias for clinical diagnostic laboratories and clinicians." (PMID 25614871, 2014). "FGFR3 is a negative regulator of bone growth and all mutations in FGFR3 are gain-of-function mutations that lead to skeletal dysplasias." (PMID 23149434, 2012). "FGFR3 is a negative regulator of bone growth and all mutations of FGFR3 are gain-of-function mutations that lead to skeletal dysplasias." (PMID 23149434, 2012). "It has been shown that the downregulation of FGFR3 mutants linked to skeletal dysplasias is compromised, and this effect prolongs the time that they signal." (PMID 22529939, 2012). "Four heterozygous variants in FGFR3 were identified in 9 cases of skeletal dysplasia." (PMID 37880672, 2023). "Several skeletal dysplasias are associated with gain-of-function mutations in FGFR3." (PMID 37296099, 2023).
skeletal dysplasia (continued). "Consequently, neutralization of the FGF ligand by an RNA aptamer represents a viable approach to treat skeletal dysplasia caused by ectopic FGFR3 activation." (PMID 34203430, 2021). "In addition, human skeletal dysplasia caused by activating FGFR3 mutations are characterized by alterations of the primary cilium." (PMID 32630309, 2020). "Humans with FGFR3 gain-of-function point mutations also present a variety of skeletal dysplasias." (PMID 31371388, 2019). "Activating mutations in FGFR3 tyrosine kinase cause several forms of human skeletal dysplasia." (PMID 19088846, 2008). "We report a newborn with prenatal suspicion of skeletal dysplasia, confirmed postnatally as TD1 via FGFR3 p.Ter807Trp mutation, highlighting the importance of prenatal counseling, early genetic confirmation, and palliative care involvement." (PMID 42083712, 2026). "Because the FGFR3-driven skeletal dysplasia models are performed using neonatal mice, an experiment was designed to understand the pharmacokinetics of TYRA-300 at a relevant efficacious dose in male and female mice, ranging from 1 to 12 weeks of age." (PMID 40178985, 2025). "Several potential therapeutic strategies have been taken to develop treatments for FGFR3 skeletal dysplasias." (PMID 37824212, 2023). "Superior bone regeneration during DO has been indicated in FGFR3-related skeletal dysplasia compared to that in other etiologies, among adolescent and young adult patients." (PMID 36927417, 2023). "Many disease-causing genes, such as LBR, SLC26A2, FLNB, COL1A2, COL2A1, and FGFR3, have been found by WES to be frequently associated with skeletal dysplasia in fetuses." (PMID 37880672, 2023). "Skeletal dysplasia (SD) is one of the most common inherited neonatal disorders worldwide, where the recurrent pathogenic mutations in the FGFR2, FGFR3, COL1A1, COL1A2 and COL2A1 genes are frequently reported in both non-lethal and lethal SD." (PMID 34789231, 2021). "This disorder is the most severe of a group of FGFR3‐related skeletal dysplasias, including the prototype achondroplasia and the mild form, hypochondroplasia." (PMID 34597445, 2021). "Activated FGFR3 results in disordered endochondral bone growth and skeletal dysplasia through impaired proliferation and differentiation of growth plate chondrocytes 9,10." (PMID 32641982, 2020). "The most common skeletal dysplasia is achondroplasia, which is part of the FGFR3 chondrodysplasia group." (PMID 32580780, 2020). "Here, we report on a Japanese girl manifesting a more severe skeletal dysplasia than classic ACH, with two de novo FGFR3 variants, the common p.G380R mutation and the p.S378N variant, both of which were located on the same allele." (PMID 31975530, 2020). "Activated FGFR3 leads to impaired growth plate chondrocyte proliferation and differentiation, resulting in disordered endochondral bone growth and skeletal dysplasia in ACH/TD." (PMID 26091072, 2015). "Although additional studies are required to prove that meclozine is indeed effective for patients with FGFR3-related skeletal dysplasias, we propose that meclozine is an attractive and potential therapeutic agent." (PMID 24324705, 2013). "Here, we screened 1,186 FDA-approved compounds to identify a clinically applicable drug that ameliorates ACH and other FGFR3-related skeletal dysplasias." (PMID 24324705, 2013). "It is conceivable that downregulation of the FGFR3 signaling alleviates the skeletal phenotype of FGFR3-related skeletal dysplasias." (PMID 24324705, 2013). "We propose that meclozine is a potential therapeutic agent for treating ACH and other FGFR3-related skeletal dysplasias." (PMID 24324705, 2013). "Because the optimal doses and adverse effects of meclozine have already been established, meclozine can be readily prescribed for FGFR3-related skeletal dysplasia after effectiveness in humans is confirmed." (PMID 24324705, 2013).
skeletal dysplasia (continued). "It has been suggested that there is a correlation between the level of FGFR3 phosphorylation and the severity of the disturbance in endochondrial ossification in human skeletal dysplasias." (PMID 22529939, 2012). "To answer this question, we compared six FGFR3 mutants, which together account for the majority of the known skeletal dysplasia cases, for their activation of STAT1 and ERK MAP kinase, and their effects on chondrocyte growth." (PMID 19088846, 2008). "The majority of evidence supporting the role of STAT1 in FGFR3 signaling in cartilage was obtained using the K650M or K650E mutants, which account for only a small subset of FGFR3-related skeletal dysplasia cases." (PMID 19088846, 2008). "Human FGFR3-related skeletal dysplasia was also summarized in a recent review." (PMID 37108419, 2023). "Molecular testing of FGFR3 variants can be performed to confirm the radiological diagnosis and there is the possibility of testing for a multi gene NGS (next-generation sequencing) panel in the case of differential diagnosis among skeletal dysplasias." (PMID 35986266, 2022). "Monogenic diseases which do not present with gross structural anomalies during early fetal development (e.g., FGFR3-related skeletal dysplasia) may be missed in the first-trimester ultrasound screening." (PMID 36229437, 2022). "We believe that RBM-007, as a direct inhibitor of FGFR3, may be used either alone or in combination with vosoritide for full restoration of skeletal growth in patients with skeletal dysplasia." (PMID 34203430, 2021). "FGFR3 gene sequencing was performed but did not identify pathogenic mutations for skeletal dysplasia." (PMID 30359267, 2018). "Targeted mutations in the mouse FGFR3 gene have replicated the phenotype of some human skeletal dysplasias to some extent but have failed to clarify the pathogenesis of scoliotic curve progression." (PMID 25852647, 2015). "Among the 1,186 FDA-approved drugs that have favorable or validated pharmacokinetic and toxicological profiles, we identified meclozine as a novel inhibitor of the FGFR3 signaling, which can potentially be applied to clinical practice for short stature in FGFR3-related skeletal dysplasias." (PMID 24324705, 2013). "Thus the ability to activate STAT1 appears restricted to the K650M and K650E-FGFR3 mutants, which however account for only a small minority of the FGFR3-related skeletal dysplasia cases." (PMID 19088846, 2008). "No effective treatments for FGFR3-related skeletal dysplasias are currently available." (PMID 24324705, 2013). "Lastly, we did not conduct the animal study of DO using inhibitors of FGFR3 signaling, although there have been several animal studies in which meclozine ameliorated bone mass in OVX mice as well as a juvenile mouse model of FGFR3-related skeletal dysplasia." (PMID 36927417, 2023). "In addition, for the general short-stature population with skeletal dysplasia, ACAN-related short stature was more responsive to rhGH treatment than NPR2-related short stature, and significant height improvement was not seen in FGFR3-related short-stature patients in this cohort." (PMID 35250876, 2022).
adenocarcinoma (12 papers, 2012 to 2025). A common cancer characterized by the presence of malignant glandular cells. "By reducing FGFR3 expression through siRNA transfection, chondrocytes exhibited enhanced proliferation when released from FGFR3 mediated growth inhibition, a finding similar to that seen in human adenocarcinoma cells." (PMID 23216972, 2012). "Significant differences can be found in the mutation rate of EGFR (60.9% vs 11.9%), KRAS (12.2% vs 25.0%), STK11 (1.5% vs 11.9%), FGFR3 (2.4% vs 0.0%) and ERBB4 (1.2% vs 6.1%) between adenocarcinoma in our cohort and TCGA-LUAD data (all p < 0.001)." (PMID 38496837, 2024). "We observed a significant increase in CNA in FGFR3, BCL3, and IDH2 in CCNE1-amplified versus nonamplified EG adenocarcinoma." (PMID 38717153, 2024).
infection (11 papers, 2010 to 2024). The state of being infected such as from the introduction of a foreign agent such as serum, vaccine, antigenic substance or organism. "In the behavioral tests, Fgfr3-iCreERT2 mice with DIO-OGT infection in the mPFC presented significantly increased immobility time in the FST." (PMID 36757814, 2023). "Infection with type II Runx2-expressing adenovirus induced Fgfr1, Fgfr2, and Fgfr3 mRNA and their IIIb and IIIc isoform mRNA." (PMID 30202094, 2018). "Furthermore, a few FGFs, which mainly activate FGFR3, inhibited infection of different cancer cell lines with Vesicular Stomatitis Virus or Coxsackie Virus B3 through as yet unidentified mechanisms that are independent of ISG regulation." (PMID 39621133, 2024). "Indeed, we previously showed that treatment of immortalized human HaCaT keratinocytes with AZD4547 and BGJ398, which inhibit the kinase activity of FGFR1, FGFR2 and FGFR3, reduces the infection with HSV-1." (PMID 39621133, 2024). "Certain strains of Escherichia coli have been shown to influence FGF signaling; FGFR3 activation by FGFs stimulates RAS, which then activates the MAPK pathway to promote cell survival, growth, and differentiation during infection." (PMID 39791702, 2024). "Concurrently, FGFR3 and TAB 3 maintained a repressed state until late infection (16 h)." (PMID 28993767, 2017). "To assess whether FGFR3-IIIc mediates migration signals, we performed migration assays with SW480 and Caco2 cells after infection with dominant-negative KD3-IIIcv and Cv." (PMID 20234367, 2010). "Pyk2 and FGFR3 may regulate HPV replication early after basal cell infection to limit viral replication and may prevent over-replication of episomes initially after infection." (PMID 34201556, 2021).
genetic disorder (9 papers, 2013 to 2025). "Some mutations result in aberrant FGFR3 signaling and are associated with various genetic disorders and oncogenic conditions." (PMID 36581204, 2023).
CNS tumors (5 papers, 2021 to 2024). "We report four cases of pediatric CNS tumors associated with NTRK (n = 2), ROS (n = 1) and FGFR3 (n = 1) oncogenic fusion genes as a proof of concept." (PMID 39409964, 2024). "FGFR3 is also downregulated in WT; however, in pediatric CNS tumors, opposite FGFR3 expression profiles are observed." (PMID 36839989, 2023). "Then, we checked the methylation level of the FGFR3 gene within the DKFZ CNS tumors to determine whether FGFR3 hypomethylation is a CN specific event." (PMID 38609519, 2024). "Remarkably, mean FGFR3 expression in PF-A, PF-SE, ST-YAP1, and ST-RELA ranked among the highest in comparison to other CNS tumor types." (PMID 34046693, 2021). "Whereas FGFR1-IIIc was also the predominant form in other CNS tumor types as well as in our FGFR-driven control cell models, only EPN cells exhibited extensive expression of FGFR3-IIIc." (PMID 34046693, 2021).
liver (3 papers, 2011 to 2023). "Surprisingly, the same FGFR3 but not PIK3CA point mutation was found in mBT liver metastasis." (PMID 33912469, 2021).
degenerative diseases (2 papers, 2014 to 2023). "Targeting the FGF-2/FGFR3 pathway may give us clues for future therapeutic strategy against neurodegenerative diseases." (PMID 24735639, 2014).
bacterial infection (1 paper, 2024). "Viral and bacterial infection increases mRNA levels of Sp-FGFR3 in the hepatopancreas and Pc-FGFR4 in hemocytes and hepatopancreas." (PMID 38638139, 2024).
cardiovascular diseases (1 paper, 2024). "At the same time, some studies have found that Klotho, FGFR1, and FGFR3 are expressed in the vascular wall, which suggests that the vascular wall is the target organ of FGF23, and also that FGF23 is involved in the occurrence and development of cardiovascular diseases." (PMID 39096857, 2024).
epithelial neoplasm (1 paper, 2014). A benign or malignant neoplasm that arises from and is composed of epithelial cells. "FGFR3 germline mutations cause skeletal disorders, while its somatic mutations have been identified in benign skin lesions and epithelial neoplasms." (PMID 25505998, 2014). "FGFR3 germline mutations cause autosomal dominant skeletal disorders, while its somatic mutations have been identified in benign skin lesions and epithelial neoplasms." (PMID 25505998, 2014).
hematological malignancies (1 paper, 2024). "In addition, 4 of the FGFR3 mutations reported here are already classified as activating in MM as well as in other hematological malignancies, solid tumors and skeletal disorders." (PMID 38684670, 2024).
musculoskeletal disorders (1 paper, 2023). "Comparing our results with eight other recent studies on fetal structural abnormalities showed that FGFR3 and COL1A1 are the most common pathogenic genes in musculoskeletal disorders, suggesting a strong genotype-phenotype correlation." (PMID 37880672, 2023).
skeletal anomaly (1 paper, 2022). "The second frequent type was FGFR3 variants, which could cause a skeletal anomaly in 12 fetuses (1.25%)." (PMID 34980134, 2022).
skeletal muscle disorder (1 paper, 2022). A disease involving the skeletal muscle tissue. "Thus, exploring the underlying mechanisms of this uncharacterized endocytosis of FGFR3 is essential in certain disease conditions (skeletal muscle disorders and malignancies) where FGFR3 is prominently dysregulated." (PMID 36010634, 2022).
FGFR3 also shares sentences with these, for which no sentence is quoted: Apert syndrome (11 papers); oligodendroglioma (9); skin cancer (6); skeletal diseases (5); stomach cancer (5); Costello syndrome (4); craniosynostosis syndromes (4); Noonan syndrome (4); Huntington disease (3); nasopharyngeal carcinoma (3); prostate adenocarcinoma (3); Saethre-Chotzen syndrome (3); skin cutaneous melanoma (3); soft tissue sarcoma (3); acromesomelic dysplasia (2); anemia (2); autism (2); autosomal dominant disease (2); Brachycephaly (2); brain cancer (2); breast invasive carcinoma (2); chronic myeloid leukemia (2); clear cell renal cell carcinoma (2); diastrophic dysplasia (2); gastrointestinal stromal tumor (2); Infertility (2); Intellectual disability (2); Kabuki syndrome (2); kidney cancer (2); lymphoid neoplasm (2).
A further 171 diseases each share a sentence with FGFR3 in 2 papers or fewer.